GPRASP3 (G protein-coupled receptor associated sorting protein family member 3)
Description:
Survival and differentiation promoting protein that plays a role in the regulation of neurosynaptogenesis. Induces phosphatase PP2A activity which results in APP dephosphorylation and inhibits BACE1-mediated processing of APP.
Synonyms: bHLHb9; p60TRP; KIAA1701; GASP3
Tractability: PROTAC: ubiquitination databases record sites on it.
Gene: Protein-coding gene on chromosome X (102,720,688 to 102,753,540, forward strand). Ensembl gene ENSG00000198908.
Subcellular location: Cytoplasm; Nucleus
Subcellular location (Human Protein Atlas): Cytosol; Nucleoplasm
Gene Ontology:
Molecular function: protein binding; protein homodimerization activity
Biological process: learning or memory; negative regulation of neuron apoptotic process; positive regulation of dendritic spine morphogenesis; positive regulation of neurogenesis; positive regulation of synapse assembly
Cellular component: cytosol; extracellular exosome; nucleoplasm; nucleus; cytoplasm
Homologues: Orthologues: chimpanzee GPRASP3 (99% identical), macaque GPRASP3 (97% identical), rabbit GPRASP3 (79% identical), dog GPRASP3 (78% identical), pig GPRASP3 (78% identical), guinea pig GPRASP3 (77% identical), mouse Bhlhb9 (73% identical), rat Gprasp3 (73% identical), zebrafish armc10 (10% identical), tropical clawed frog armc10 (9% identical), Caenorhabditis elegans Y67A10A.7 (8% identical). Paralogues in human: GPRASP1 (32% identical), GPRASP2 (32% identical), ARMCX5 (25% identical), ARMCX4 (22% identical), ARMC10 (13% identical), ARMCX1 (13% identical), ARMCX3 (12% identical), ARMCX2 (12% identical), ARMCX6 (9% identical), ARMC12 (7% identical).
Diseases named in the same sentence as GPRASP3 in open-access papers:
GPRASP3 is named in the same sentence as 3 diseases in open-access papers, as found by Europe PMC text mining. Sharing a sentence is not in itself a finding about the gene and the disease.
GPRASP3 shares sentences with these, for which no sentence is quoted: tumor (3 papers); Alzheimer disease (1); neurodegenerative disease (1).